LEP (leptin)
Diseases named in the same sentence as LEP in open-access papers (continued):
Sharing a sentence is not in itself a finding about the gene and the disease.
obesity syndrome (6 papers, 2010 to 2025). "In contrast to some monogenic obesity syndromes, which display classical Mendelian inheritance (LEP, LEPR, POMC and PCSK1), rare heterozygous variants in HTR2C are generally not fully penetrant." (PMID 36536256, 2022). "The mouse model harboring leptin V145E mutation will provide new information on the current understanding of leptin biology and novel mouse model for the study of human obesity syndrome." (PMID 21151569, 2010). "Finally, the V145E substitution in the N-terminus of helix D supplements the known mutations in human and mouse leptin and thereby offers novel mouse model for the study of human obesity syndrome." (PMID 21151569, 2010). "Hyperleptinemia, the consequence of increased leptin secretion and reduced leptin clearance, is a characteristic of the obesity syndrome." (PMID 35527735, 2022). "Two Leptinob/ob mouse lines with spontaneously mutated leptin cannot completely model human obesity syndrome because the leptin protein is completely lacking in the serum of those mice." (PMID 21151569, 2010).
parasitic infections (6 papers, 2018 to 2025). "Aberrant leptin levels may induce an altered inflammatory response and increased susceptibility to bacterial, viral, and parasitic infections." (PMID 33907162, 2021). "Thus, leptin has been placed at the center of many interrelated functions in various pathogenic conditions, such as bacterial, viruses and parasitic infections." (PMID 30534129, 2018). "Furthermore, leptin exerts central effects on hypothalamic-pituitary function and disruption of these effects have been implicated into severe parasitic diseases due to immune dysfunction in host." (PMID 30534129, 2018). "Patients who had multiple parasitic infections were more likely to had higher leptin concentrations than those who were parasite-free." (PMID 41239264, 2025). "The significant association found in the current study between logFEC and LEPR_260 in the Corriedale breed validates previous studies conducted in other breeds of leptin’s involvement with the immune response in the presence of a parasitic infection." (PMID 36140716, 2022). "There are few contradictory reports, which suggest that leptin levels increased during parasitic infection in children." (PMID 29868503, 2018). "However, high serum leptin levels were reported in several parasitic infections, possibly due to acute inflammation and production of IL-1β, TNF-α and IL-6 caused by the gut infections." (PMID 32824322, 2020). "For instance, in eosinophils, human leptin plays a key role in the host defense system against parasitic infections and, thus, the level of eosinophilia might indicate the relative severity of the infection due to the invasion by the parasites." (PMID 32824322, 2020). "Moreover, very little is known about the role of leptin in pathogenesis of parasitic infections." (PMID 30534129, 2018).
prostate tumor (6 papers, 2012 to 2020). "Larger volume prostate tumors and higher histological grade PCa have been associated with significantly higher serum leptin levels than less volume or less advanced tumors." (PMID 32573960, 2020). "Therefore, there is increased availability of leptin for binding to the long leptin receptor signaling isoform in the prostate tumor cell membrane." (PMID 22792137, 2012). "Analysis of RNAseq data for 52 normal prostate (control) and 498 prostate adenocarcinoma obtained from TCGA database, revealed that LEP, LEPR, JAK2 and STAT3 are statistically significant downregulated in prostate tumors in relation to normal (control) prostate." (PMID 31671654, 2019).
psoriatic arthritis (6 papers, 2012 to 2025). Joint inflammation associated with psoriasis. "Patients with psoriatic arthritis exhibit higher serum levels of omentin and leptin, but lower levels of adiponectin and chemerin, compared with healthy controls." (PMID 30917508, 2019). "Those researchers also described finding a positive correlation between leptin and Psoriatic Arthritis Joint Activity Index scores." (PMID 30917508, 2019). "TNF-α, RANKL and leptin were positively correlated with Psoriatic Arthritis Joint Activity Index (PsAJAI)." (PMID 23144698, 2012). "Interestingly, whereas higher serum levels of omentin and leptin are positively correlated with numbers of osteoclast precursors in peripheral blood, lower serum adiponectin levels in psoriatic arthritis are negatively correlated with osteoclast precursors." (PMID 30917508, 2019). "Leptin might serve as a marker of severity in psoriatic arthritis patients." (PMID 23144698, 2012).
acute myeloid leukemia (5 papers, 2011 to 2026). Acute myeloid leukemia (AML) is a group of neoplasms arising from precursor cells committed to the myeloid cell-line differentiation. "; 5) Despite many studies demonstrating the protective effects of leptin against acute myeloid leukemia (AML), the role of leptin in CML remains unclear." (PMID 21991326, 2011). "Leptin is abundant within marrow adipose tissue, yet its impact on acute myeloid leukemia (AML) therapy response is undefined." (PMID 41730833, 2026).
adolescent idiopathic scoliosis (5 papers, 2012 to 2021). A scoliosis with no known cause arising in adolescent. "Leptin has been suggested to play a role in the etiology of Adolescent Idiopathic Scoliosis (AIS), however, the leptin levels in AIS girls are still a discrepancy, and no in vitro study of leptin in AIS is reported." (PMID 22615788, 2012). "Recent meta-analysis studies show that leptin levels in serum were significantly lower in adolescent idiopathic scoliosis (AIS) patients compared to healthy controls, and in terms of ghrelin levels, patients with AIS had higher levels of ghrelin than in healthy controls." (PMID 34356550, 2021). "Recent studies have focused on understanding how leptin and ghrelin signaling may play a role in adolescent idiopathic scoliosis (AIS)." (PMID 33121521, 2020).
Airway obstruction (5 papers, 2015 to 2023). Obstruction of conducting airways of the lung. "The link between adipose tissue and chronic lung disease is unclear at this time, however there is accumulating evidence for a causative role including adipocyte derived mediators such as leptin in obstructive lung disease and a link between cardiovascular disease and COPD." (PMID 31370853, 2019). "We have also reported that leptin relieves upper airway obstruction during sleep, acting in the forebrain but not in the hindbrain, where NTS is located." (PMID 34201760, 2021). "A significant negative correlation between TARC and leptin with the ratio FEV1/FVC (%) was determined, suggesting the role of both cytokines in higher degrees of airways obstruction." (PMID 38111019, 2023).
anxiety disorder (5 papers, 2015 to 2022). A category of psychiatric disorders which are characterized by anxious feelings or fear often accompanied by physical symptoms associated with anxiety. "Leptin was associated in a sex-dependent manner with the neurobiology of anxiety disorders because female carriers of the A allele of LEP rs3828942 showed a higher risk for GAD, while leptin levels seemed to be lower in men with GAD who were carriers of the A allele." (PMID 35627229, 2022). "In conclusion, the findings suggest that higher neuroticism, independent of diagnosis of current MDD or anxiety disorder, is associated with elevated levels of L/A ratio, leptin and IL-6 in young adults with and without psychiatric co-morbidity." (PMID 33963214, 2021). "Researchers have suggested that anxiety disorders impair the regular functions of the hypothalamic-pituitary-adrenal (HPA) axis, causing an increase in appetite due to alterations in the two hormones, ghrelin and leptin." (PMID 32110904, 2020). "Out of these biomarkers, neuroticism was positively associated with the L/A ratio, leptin and IL-6, independent of current diagnosis of MDD or anxiety disorder." (PMID 33963214, 2021).
Atrophy (5 papers, 2010 to 2025). Any weakening or degeneration, especially through lack of use. "Thus, the core role of the FAPs‐leptin‐PPARα axis in regulating intramuscular lipid metabolism, as revealed in this study, provides important insights into the pathophysiological mechanisms underlying human disuse muscle atrophy." (PMID 41305914, 2025). "Deficiencies of leptin or leptin receptor in mice elicit chronic thymic atrophy suggesting a key regulatory role for leptin in thymopoiesis." (PMID 20546588, 2010). "The association between FMI and leptin differed between groups, and was significantly stronger for Atrophy (103.6 % per kg/m2, p = 0.02 vs. Non-Lipo) and Controls (72.4 % per kg/m2, p < 0.001 vs. Non-Lipo) than for Non-Lipo (30.0 % per kg/m2)." (PMID 26244048, 2015). "In addition, several studies have suggested that leptin provides a stimulatory role for T-cell development in situations of acute thymic atrophy, such as starvation, immunosuppressive therapy, or infection; but leptin administration does not augment thymopoiesis in normal (non-obese) mice." (PMID 38031726, 2023).
autism spectrum disorder (5 papers, 2019 to 2024). A spectrum of developmental disorders that includes autism, and Asperger syndrome. "Available data on the association between leptin and autism spectrum disorder (ASD) are confusing." (PMID 36902307, 2023). "Increasing evidence suggests that leptin is involved in the pathology of autism spectrum disorder (ASD)." (PMID 38951775, 2024). "Elevated circulating leptin levels have been observed in patient with neurodevelopmental disorders such as Autistic spectrum disorder (ASD) and Rett syndrome and in animal models of the diseases." (PMID 33183317, 2020). "An interesting finding suggested that there is an up-regulation in circulating leptin in children suffering from different forms of neurodevelopmental disorders, one of which being autism spectrum disorders." (PMID 30975733, 2019). "Furthermore, a postmortem study with brain tissue showed higher concentrations of leptin, together with a number of proinflammatory and modulatory cytokines, in the anterior cingulate gyrus of patients with autism spectrum disorders (ASD) than in that of controls." (PMID 36902307, 2023).
behavioral disorders (5 papers, 2018 to 2025). "This indicated that cord blood leptin level was independently associated with child behavioral problems." (PMID 29324697, 2018). "In another study, leptin was analyzed in depressive patients with therapy, finding a relationship between the combination of serum leptin and number of behavior disorders, suggesting that leptin levels can be a predictor of treatment responses in these patients." (PMID 36674935, 2023). "However, long-term exposure to elevated leptin levels may lead to mental/behavioral disorders related to the feeding and reward systems." (PMID 34884416, 2021).
cholestasis (5 papers, 2022 to 2025). Impairment of the bile flow caused by obstruction within the liver, or outside the liver in the bile duct system. "Elevated leptin has been observed in other animal models of cholestasis and appears to exacerbate the disease." (PMID 39667808, 2024).
cognitive disorder (5 papers, 2010 to 2024). A disease affects cognitive processes. "After this role is well-established and fully characterised, leptin replacement may be regarded as a therapeutic agent in cognitive diseases, particularly in AD." (PMID 21070531, 2010).
colon adenocarcinoma (5 papers, 2016 to 2023). "Likewise, in the colon adenocarcinoma SW480 cell line, FAK activation induced by leptin is also dependent on integrins activation." (PMID 31554180, 2019).
Cushing syndrome (5 papers, 2017 to 2024). Cushing's syndrome (CS) encompasses a group of hormonal disorders caused by prolonged and high exposure levels to glucocorticoids that can be of either endogenous (adrenal cortex production) or exogenous (iatrogenic) origin. "The five keywords with the longest duration of burst were diurnal rhythm (1994–2010), messenger rna (1999–2014), receptor (2002–2016), cushings syndrome (1991–2005), leptin (1998–2011)." (PMID 39839286, 2024). "In veterinary medicine, a study reported changes in leptin concentrations before and after treatment in dogs with naturally occurring pituitary-dependent hyperadrenocorticism." (PMID 31238989, 2019).
diabetic retinopathy (5 papers, 2009 to 2025). "A particularly important consideration with regard to correctly interpreting the mechanisms of diabetic retinopathy underlying mouse models of diabetic retinopathy is the combination, in our study, of the BTBR genetic background and leptin deficiency." (PMID 30094465, 2018). "High plasma leptin level have been found to relate to both hypertensive and diabetic retinopathy." (PMID 24347825, 2013). "Some processes relevant to diabetic retinopathy were found upregulated in diabetic aqueous samples including CD40, C reactive protein, erythropoietin, fatty acid binding protein, FGF basic, fibrinogen, IL-1ra, IL-8, leptin, macrophage-derived chemokine (MDC), MMP-2, and VEGF." (PMID 19145248, 2009).
esophagitis (5 papers, 2014 to 2022). An acute or chronic inflammatory disease affecting the esophageal wall. "However, correlations of ghrelin levels with the severity of esophagitis, leptin and ghrelin levels with the severity of GERD symptoms, and leptin levels with lower esophageal pH were found." (PMID 34768715, 2021).
Huntington disease (5 papers, 2012 to 2023). Huntington disease (HD) is a rare neurodegenerative disorder of the central nervous system characterized by unwanted choreatic movements, behavioral and psychiatric disturbances and dementia. "The reduction of miR-24-3p may be the reason for the increase of the fat mass and leptin levels during the treatment improvement of HD (Huntington’s disease) patients." (PMID 34249911, 2021). "Conceivably, its metabolic function could be mediated by circulating leptin and adiponectin and/or IGF-1, which are perturbed by Huntington’s disease mutations in mammals." (PMID 27809764, 2016).
hypopituitarism (5 papers, 2020 to 2024). A condition of diminution or cessation of secretion of one or more hormones from the anterior pituitary gland. "Moreover, leptin levels are significantly increased in patients with hypopituitarism, indicating a “leptin resistance” state." (PMID 39502571, 2024). "Another recent retrospective study including surgical and nonsurgical hypopituitarism patients revealed that liver fibrosis grade had a rapid increase in surgery cases of NAFLD patients with hypopituitarism, which correlated significantly with leptin serum levels." (PMID 33505943, 2021).
injury (5 papers, 2013 to 2022). Damage inflicted on the body as the direct or indirect result of an external force, with or without disruption of structural continuity. "Leptin also plays a crucial role in the development of neuropathic pain in animal models of nerve injury and has been demonstrated to cause allodynia and hyperalgesia (which are hallmarks of neuropathic pain conditions but also of central sensitization and nociplastic pain)." (PMID 35063029, 2022). "In the context of brain injury, LEP and its receptor protein may be expressed from many brain regions, which may be involved in regulation of the central nervous system (CNS)." (PMID 35928129, 2022). "The mechanism of this action may be relevant to the neuroprotective role of leptin under conditions of nerve injury." (PMID 24325936, 2013). "It has been shown that correcting leptin and adiponectin levels can prevent profibrogenic responses by inhibiting TGF-β in experimental models of NASH and chemicals-induced liver injury." (PMID 34593018, 2021).
Lipedema (5 papers, 2020 to 2025). Disorder of adipose tissue characterized by symmetric and bilateral enlargement of the lower extremities due to abnormal deposition of subcutaneous fat often in obese women. "In these studies, adipocytes derived from femoral stem cells of lipedema patients (15% stage 1, 70% stage 2) displayed higher leptin expression compared to the controls." (PMID 40149538, 2025). "Based on the common traits observed in obese patients, research up to date has focused on the analysis of adiponectin, leptin, visfatin, and resistin as potential biomarkers for lipedema." (PMID 40149538, 2025). "Pain and allodynia are significant symptoms in patients with lipedema, and they have increased levels of leptin and achieve pain relief after liposuction." (PMID 37559026, 2023). "In lipedema, systemic levels and the adipocyte expression of the classical adipokines adiponectin and leptin appear normal, while it remains unclear if markers of inflammation and oxidative stress are increased." (PMID 40149538, 2025). "However, despite the accumulation of subcutaneous fat, the limited information that is currently available documents that women with lipedema have rather normal levels of adiponectin, leptin, visfatin, and resistin." (PMID 40149538, 2025). "The leptin and PPAR-γ gene expression showed a significant increase in differentiated adipocytes from lipedema ASCs-T (p = 0.04) and ASCs-A (p = 0.03), respectively, compared to adipocytes differentiated from Healthy ASCs." (PMID 32059474, 2020). "The ratio of adiponectin and leptin levels was significantly lower in adipocytes from obese lipedema donors compared to their non-obese counterparts." (PMID 40149538, 2025). "The leptin gene expression was significantly increased in lipedema adipocytes differentiated from ASCs-T (p = 0.04) and the PPAR-γ expression was significantly increased in lipedema adipocytes differentiated from ASCs-A (p = 0.03) compared to the corresponding cells from healthy patients." (PMID 32059474, 2020). "Leptin (LEP) and adiponectin (ADIPOQ), markers mainly expressed by mature adipocytes, showed no significantly different gene expression in any sample types, suggesting an alteration of early preadipocyte determination, rather than late differentiation in lipedema." (PMID 35625899, 2022).
Lipoatrophy (5 papers, 2014 to 2026). Localized loss of fat tissue. "Some studies have reported lower leptin levels in patients with lipoatrophy." (PMID 41596392, 2026). "Furthermore, in contrast to generalized lipoatrophy, which is characterized by abnormally low leptin levels, the plasma or serum leptin levels in acquired partial lipoatrophy are low but still within the normal range, which makes the diagnosis challenging." (PMID 30545408, 2018). "In contrast, others have reported that leptin in plasma is unlikely to play a major role in the genesis of lipoatrophy." (PMID 41596392, 2026).
liver dysfunction (5 papers, 2010 to 2018). "We investigated serum concentrations of total adiponectin (Acrp30), leptin, and resistin in patients with chronic alcohol abuse and different grades of liver dysfunction, as well as ALD complications." (PMID 24259947, 2013). "Several studies investigated whether circulating leptin levels are correlated with severity of liver dysfunction." (PMID 28661458, 2017). "Therefore, the objective of the present study was to determine serum concentrations of total adiponectin (Acrp30), leptin, and resistin in patients with chronic alcohol abuse and different grades of liver dysfunction." (PMID 24259947, 2013).
memory impairment (5 papers, 2017 to 2025). "The involvement of the hippocampus in memory processes is well known, and leptin has been implicated in memory impairment in obese populations." (PMID 35743474, 2022). "In human studies, decreased leptin levels is associated with increased Aβ deposition and memory impairment, reinforcing how leptin resistance within the brain may exacerbate AD-related pathologies." (PMID 34497507, 2021). "These metabolic consequences may contribute to hippocampal-dependent memory impairment, accompanied by a lower central leptin level, and a higher SCD1 gene expression in the brain." (PMID 28621759, 2017).